GPX4 (glutathione peroxidase 4)
Diseases named in the same sentence as GPX4 in open-access papers (continued):
Sharing a sentence is not in itself a finding about the gene and the disease.
breast carcinoma (continued). "Protein levels of GPX4, SLC7A11, and SLC3A2 in four luminal breast cancer cell lines (MDAMB415, ZR75-1, MCF7, and CAMA1), four basal breast cancer cell lines (MDAMB436, MDAMB231, HCC1937, and HCC1806), and one normal breast epithelial cell line (MCF10A) were concordant with mRNA expression." (PMID 37596261, 2023). "Ketamine inhibits GPX4 levels and inhibits histone H3 lysine 27 acetylation (H3K27ac) and enrichment of RNA polymerase II (RNA pol II) by attenuating KAT5 on the GPX4 promoter in breast cancer cells." (PMID 36467032, 2022). "used breast cancer cells (MDA-MB-231, SUM159, BT-574) and found that DMOCPTL directly bound to the glutathione peroxidase 4 (GPX4) to up-regulate early growth response 1 (EGR1) in TNBC cells, leading to apoptosis of mitochondrial mediator and further inhibiting breast tumor growth." (PMID 36568247, 2022). "Recently, it has also been shown that ferroptosis‐related genes such as GPX4 and SLC7A11, could serve as a novel biomarker for predicting the prognosis in breast cancer (another class of BRCA‐related cancer) patients." (PMID 36485069, 2022). "In addition, Metformin a commonly used hypoglycemic drugs in clinical practice, was found to promote ferroptosis in breast cancer cells by inhibiting the UFMylation of SLC7A11 and the transcription of GPX4." (PMID 36105219, 2022). "Our results thus far suggest that xCT positive breast cancer cells—Those expressing high levels of both SLC7A11 and SLC3A2—Are able to drive GPX4 expression through the selenocysteine biosynthesis pathway, and also are able to resist lipid prooxidant-induced death." (PMID 33672555, 2021). "Additionally, GPX4 and CDK4/6 inhibitors work in concert to treat breast cancer." (PMID 40969276, 2025). "For instance, direct pharmacological inhibition of GPX4’s enzymatic activity with agents like RSL3, or depletion of GSH by blocking the upstream transporter SLC7A11 with inhibitors such as erastin, both lead to a sharp increase in intracellular LOOH levels in breast cancer cells." (PMID 41008615, 2025). "Selective inhibition of GPX4-mediated glutathione synthesis and FSP-mediated coenzyme Q10 reduction using nano-catalytic particles was successfully used to induce pronounced ferroptotic cell death in chemotherapy-resistant breast cancer cells and animal models." (PMID 40227202, 2025). "Selenophosphate synthetase 2, an enzyme involved in selenocysteine biosynthesis, has been found to be selectively essential for the survival of malignant cells but not in normal cells, especially in cancers that rely on GPX4 to protect cancer cells against ferroptosis such as breast cancer." (PMID 40227202, 2025). "Indeed, in the TBCP-1 breast cancer cell line, though neratinib did not alter GPX4 protein level, neratinib downregulated SLC3A2 expression and cysteine import." (PMID 39002022, 2024). "METTL16 reduced the m6A methylation level of iron-dead GPX4 mRNA and significantly promoted the degradation of GPX4 mRNA, suggesting that METTL16 enhances the expression level of GPX4 through m6A modification, and thus inhibits iron-death to promote the proliferation of breast cancer cells." (PMID 39289775, 2024). "In a study conducted by Kuang, it was discovered that indirubin stimulates lipid peroxidation in breast cancer cells, resulting in reduced glutathione (GSH) levels, increased malondialdehyde (MDA) and 4‐Hydroxynonenal (4‐HNE) levels and decreased glutathione peroxidase 4 (GPX4) expression." (PMID 38140764, 2024). "We found that GPX4, but not the xCT transporter, is selectively elevated in luminal breast cancer." (PMID 37596261, 2023). "In a panel of breast cancer and nontransformed immortalized breast epithelial cell lines, we find the breast cancer lines to be resistant to hydrogen peroxide, consistent with increased GPX4 function." (PMID 33672555, 2021). "However, the specific mechanism of GPx4 in the occurrence of breast cancer has not been elucidated and requires further study." (PMID 32571353, 2020).
breast carcinoma (continued). "Unexpectedly, while breast cancer cells are resistant compared to nontransformed cells against oxidative stress inducing drugs, at the same time they are hypersensitive to lipid peroxidation and ferroptosis induced by Erastin or Rsl-3, indicating that they are ‘addicted’ to the xCT/GPX4 axis." (PMID 33672555, 2021). "It is important to investigate how both classical pathways, such as GPX4/ACSL4 ferroptosis signaling, and non-classical pathways, like GPX4-independent ferroptosis, influence breast cancer progression, invasion, and metastasis." (PMID 39664391, 2024). "Unlike GPX4, which has been demonstrated to be downregulated in breast cancer cells, ACSL4 has been verified to be substantially expressed in breast cancer tissues." (PMID 37488128, 2023). "The important role of AR in regulating GPX4 expression has recently been confirmed by AR overexpression in HEK‐293 cells and AR knockdown in ferroptosis‐resistant triple‐negative LAR breast cancer cells, and this counter‐regulation correlates with ferroptosis sensitivity." (PMID 36658724, 2023). "GPX4, GPX6 and GPX7 had no significant predictive values for prognosis of breast cancer." (PMID 32782436, 2020). "Overall, considering both the CCLE and LINCS datasets, eight selenoproteins were overexpressed (DIO2, GPX1, GPX4, SELENOI, SELENON, SELENOS, TXNRD1 and TXNRD3) and five were down-expressed (DIO1, GPX2, GPX3, SELENOP and SELENOW) in TNBC compared to all other “non-TNBC” breast cancer subtypes." (PMID 35158912, 2022).
lung cancer (122 papers, 2018 to 2026). A malignant neoplasm involving the lung. "Studies have shown that high expression of SLC7A11 is closely associated with the proliferation and survival of lung cancer cells, while the expression of GPX4 is linked to chemo resistance." (PMID 39917300, 2025). "Plenty of research has identified the crucial part of GPX4 in the susceptibility to drug-mediated ferroptosis in lung cancer, and targeting GPX4 can re-sensitize drug-resistant lung cancer to chemotherapy drugs." (PMID 38783959, 2024). "GPX4 is upregulated in many patients with lung cancers and causes resistance to epidermal growth factor receptor-tyrosine kinase inhibitors (EGFR-TKIs), radiotherapy, and immune checkpoint inhibitors." (PMID 39104501, 2024). "Further investigation is needed to understand the roles of GPX4 in lung cancer tumorigenesis and its underlying mechanisms responsible for survival." (PMID 36443446, 2022). "In general, these data suggested that the notable GSH high‐consumption state in lung cancer BM was caused by the upregulation of GPX4 and GSTM1." (PMID 34586745, 2021). "In short, GPX4 is linked to the occurrence and progression of lung cancer and may become a new target for lung cancer targeted therapy." (PMID 40969276, 2025). "Many natural products can cause GPX4 degradation in lung cancer and induce ferroptosis." (PMID 39104501, 2024). "The mechanisms underlying these discrepancies in different lung cancer cell lines remain unknown but could relate to other genetic factors that might have influenced NRF2 regulation of GPX4 expression." (PMID 35459868, 2022). "Mechanistically, circAFF4 bound to the deubiquitinating enzyme USP10, which in turn suppressed USP10-mediated deubiquitination of GPX4, and enhanced the ubiquitin-dependent proteasome degradation of GPX4, thereby facilitating ferroptosis in lung cancer cells." (PMID 42010438, 2026). "CONCLUSIONS: Our findings reveal a novel mechanism by which circAFF4 interacts with USP10, impairing USP10-mediated stabilization of GPX4, promoting ferroptosis in lung cancer cells, and ultimately suppressing lung cancer progression." (PMID 42010438, 2026). "Our findings identified GPX4 as the most critical downstream factor involved in NLN-induced ferroptosis in lung cancer cells, with its expression significantly suppressed following NLN knockdown." (PMID 41242017, 2025). "Mechanistically, IO induces ferroptosis by modulating the SIRT6/Nrf2/GPX4 signaling pathway, thereby reversing drug resistance in lung cancer." (PMID 40191731, 2025). "To elucidate the potential mechanism by which the combined treatment induces ferroptosis in lung cancer cells, we evaluated its effect on the Nrf2/HO-1/GPX4 antioxidant axis, considering that the decreased GSH is upstream of this pathway." (PMID 40539046, 2025). "In the present study, we demonstrated that LDR combined with an ICI can induce ferroptosis in lung cancer, leading to tumor suppression and exerting a significant anti-tumor effect via activation of the Nrf2/HO-1/GPX4 axis." (PMID 40539046, 2025). "Mechanistically, zerumbone and gefitinib can suppress lung cancer growth by inducing ferroptosis through the downregulation of GPX4, thereby enhancing the sensitivity of lung cancer cells to platinum-based chemotherapy drugs." (PMID 40191731, 2025). "Studies indicate that DHA can enhance the release of ROS generated by PDT by inhibiting GPX4 and inducing iron death, thereby improving its cytotoxic effect on lung cancer cells." (PMID 40191731, 2025). "A deeper understanding of GPX4’s mechanisms in lung cancer can help develop more targeted and efficient treatment modalities in the future, leading to better clinical outcomes and survival rates for patients." (PMID 40191731, 2025). "Our analysis also indicated that the three members of the aldo-keto-reductase-1C (AKR1C) family (AKR1C1, AKR1C2, AKR1C3) correlated with resistance to GPX4 inhibitors in lung cancer CLs." (PMID 39995872, 2025).
lung cancer (continued). "Prior investigations into ferroptosis in lung cancer have largely focused on regulators like GPX4 or SLC7A11; in contrast, our work captures a broader ferroptosis-linked transcriptomic signature with direct prognostic implications." (PMID 41007424, 2025). "As an important rate‐limiting enzyme in fatty acid oxidation, CPT1A was reported to stabilize c‐Myc and activate the NRF2/GPX4 system to suppress ferroptosis and improve the efficacy of immunotherapy in lung cancer cells." (PMID 39811936, 2025). "GPX4 inhibitor RSL3 can enhance the sensitivity of lung cancer cells to cisplatin in vivo and in vitro." (PMID 40191731, 2025). "These in vivo and in vitro data confirm that LDR combined with ICI therapy can induce ferroptosis in lung cancer cells by suppressing the Nrf2/HO-1/GPX4 axis." (PMID 40539046, 2025). "Depletion of NLN inhibits m6A modification of GPX4 mRNA, leading to degradation of GPX4 mRNA, leading to ferroptosis in lung cancer cells." (PMID 41242017, 2025). "Our study revealed that the combination therapy can induce an increase in ROS levels while suppressing the Nrf2/HO-1/GPX4 antioxidant pathway, leading to ferroptosis in lung cancer cells." (PMID 40539046, 2025). "For example, certain chemotherapeutic agents, such as cisplatin, paclitaxel, and gemcitabine, can promote ferroptosis in lung cancer cells by elevating reactive oxygen species (ROS) and iron levels, as well as by inhibiting GPX4 and the Xc-system." (PMID 41242017, 2025). "Overall, circRNAs are emerging as vital regulators of ferroptosis in lung cancer by functioning as miRNA sponges (e.g., circDTL/miR-1287-5p/GPX4 axis) and influencing redox homeostasis." (PMID 40078365, 2025). "Studies have demonstrated that curcumin can reduce the growth and stem cell-like characteristics of lung cancer cells by inducing ferroptosis through the downregulation of GPX4 expression." (PMID 40191731, 2025). "On the one hand, Huaier significantly reduces the antioxidant capacity of lung cancer cells by downregulating the SLC7A11/GPX4 pathway, thereby increasing their sensitivity to ferroptosis." (PMID 40623982, 2025). "This study demonstrated that LDR plus ICI induces ferroptosis through the Nrf2/HO-1/GPX4 pathway, resulting in a significant anti-tumor effect and providing a combinatorial strategy to overcome lung cancer." (PMID 40539046, 2025). "This study is the first to demonstrate that the inhibition of NLN induces ferroptosis in lung cancer cells, elucidating the regulation of GPX4 expression by m6A modification and enriching the complexity of the ferroptosis regulatory network." (PMID 41242017, 2025). "The reason for this stems from the differences in both response to FTIs and differences in ferroptosis defense systems where STK11/KEAP1-mutant lung cancer harbors very effective anti-ferroptosis systems through SLC7A11/GPX4, AIFM2, and AKR1C." (PMID 39995872, 2025). "Mechanically, we found that NLN contribute to lung cancer progression by modulating the m6A modification of GPX4 mRNA, which in turn inhibits ferroptosis and promotes tumor survival." (PMID 41242017, 2025). "Lung cancer cells are vulnerable to iron-dependent oxidation of phospholipids leading to ferroptosis, a process countered by glutathione peroxidase-4 that converts lipid hydroperoxides to lipid alcohols using glutathione as reducing agent." (PMID 41529526, 2025). "Our in vitro findings demonstrate that suppression of the Nrf2/HO-1/GPX4 axis is a possible mechanism by which the combined treatment induces ferroptosis in lung cancer cells." (PMID 40539046, 2025). "Our data showed that the LDR combined with ICI treatment significantly suppressed the Nrf2/HO-1/GPX4 axis, indicating an impaired antioxidant system in lung cancer cells." (PMID 40539046, 2025).
lung cancer (continued). "DHA downregulated the SLC7A11 expression and reduced the GSH and GPX4 levels along with increasing the cellular lipid ROS level in lung cancer cells, hepatocellular carcinoma cells, and head and neck carcinoma cells." (PMID 39021832, 2024). "Recent studies have emphasized the therapeutic potential of targeting ferroptosis-related pathways, such as system Xc− inhibition and GPX4 degradation, for overcoming therapy resistance and suppressing metastasis in lung cancer." (PMID 39944353, 2024). "In summary, our findings suggest that the xCT (SCL7A11)/Nrf-2 axis, in conjunction with GPX4, plays a critical role in the regulation of mitochondrial function by SA in lung cancer cells." (PMID 39430236, 2024). "Based on current research, the targets of ferroptosis in lung cancer mainly focus on the regulation of antioxidant pathways, among which GPX4 and SLC7A11 are the core targets of GSH-dependent antioxidant pathways." (PMID 38783959, 2024). "For example, combined treatment of hemin and ionizing radiation increased ferroptosis radiosensitivity of lung cancer cells through promoting lipid peroxidation, ROS production, and GPX4 degradation." (PMID 38892219, 2024). "Isoorientin enhances ferroptosis while overcoming drug resistance in lung cancer via the SIRT6/Nrf2/GPX4 signaling axis." (PMID 38515565, 2024). "In studies focusing on lung cancer, directing efforts towards GPX4 has demonstrated the capability to trigger ferroptosis in lung adenocarcinoma cells." (PMID 39944353, 2024). "The application of GPx4 siRNA or the GPx4 inhibitor Rsl-3 has been shown to markedly suppress the proliferation and migration of lung cancer cells." (PMID 39839762, 2024). "The majority of the studies discussing the inhibitory effects of natural products in lung cancer introduced GPX4 as a promising target that can be downregulated." (PMID 39104501, 2024). "Numerous investigations have highlighted the significant impact of modulating the ubiquitination of GPX4 on the process of ferroptosis in lung cancer." (PMID 38515565, 2024). "DT induced ferroptosis and apoptosis of breast and lung cancer cells by repressing GPX4 expression, thus significantly inhibiting tumor growth without adverse effects in a xenograft nude mouse model." (PMID 39021832, 2024). "Dihydroartemisinin (DHA), known for its potent GPX4 inhibitory properties, induces a notable shift in macrophage phenotype towards M1, particularly in the context of lung cancer." (PMID 39104501, 2024). "By downregulating GPX4 for ferroptosis induction, miR-324-3p attenuates cisplatin resistance in lung cancer cells, and miR-450b-5p suppresses sorafenib resistance in liver cancer cells." (PMID 38892270, 2024). "Platinum inhibits iron cell apoptosis by high depletion of GSH through activation of the Wnt/NR2F2/GPX4 pathway.GPX4 inhibitors have been found to enhance the anticancer effects of Platinum providing new therapeutic ideas for lung cancer patients." (PMID 38562175, 2024). "In lung cancer, several proteins have been identified to modulate the ferroptosis process and influence tumor fates, among which GPX4 and FSP1 can reduce the sensitivity of lung cancer to ferroptosis by enhancing cellular antioxidant capacity." (PMID 38700533, 2024). "In lung cancer cells, manipulation of GPX4 expression changed the content of corresponding markers and cell viability, suggesting that GPX4 controls the occurrence of ferroptosis." (PMID 37188685, 2023). "For example, curcumenol decreased FTH1 levels by targeting miR-19b-3p via lncRNA H19 while inhibiting some factors, such as GPX4 and Nrf2, to increase ROS levels to trigger ferroptosis in lung cancer cells." (PMID 37833746, 2023).